SNORD116-29 (small nucleolar RNA, C/D box 116-29)
Synonyms: HBII-85-29
Gene: Small nucleolar RNA gene on chromosome 15 (25,106,521 to 25,106,603, forward strand). Ensembl gene ENSG00000207245.
Gene Ontology:
Biological process: RNA processing
Cellular component: nucleolus
Homologues: Orthologues: chimpanzee SNORD116 (100% identical), macaque SNORD116 (94% identical), rabbit SNORD116 (80% identical), mouse Gm22373 (58% identical), rat LOC120100337 (49% identical). Paralogues in human: SNORD116-25 (82% identical), SNORD116-26 (82% identical), SNORD116-27 (82% identical), SNORD116-30 (82% identical), SNORD116-16 (78% identical), SNORD116-2 (78% identical), SNORD116-20 (78% identical), SNORD116-24 (78% identical), SNORD116-6 (78% identical), SNORD116-14 (77% identical), SNORD116-17 (77% identical), SNORD116-19 (77% identical), and 20 more.